EGFR (epidermal growth factor receptor)
Diseases named in the same sentence as EGFR in open-access papers (continued):
Sharing a sentence is not in itself a finding about the gene and the disease.
cancer (continued). "Epidermal growth factor receptor (EGFR) and human epidermal growth factor receptor 2 (HER2) protein tyrosine kinases co-expressed in various cancers such as ovarian, breast, colon, and prostate subtypes." (PMID 37096560, 2023). "The epidermal growth factor receptor (EGFR) and B-Raf proto-oncogene, serine/threonine kinase (BRAF) are both well-studied kinases that play crucial roles in cancer progression." (PMID 38138441, 2023). "The recent improvements in cancer research showed the importance of HER3 tumorigenesis, progression, and primary/acquired resistance to HER2- or EGFR-targeted therapy." (PMID 37947595, 2023). "These gene sets contain several genes that have been widely studied in the context of cancer, including WNT16, CEBPD and EGFR." (PMID 37381036, 2023). "Previous studies have demonstrated that TGFα is a more potent agonist for EGFR than EGF in various biological systems, highlighting the significance of CAF-derived TGFα in regulating EGFR-mediated cancer cell chemoresistance." (PMID 37821657, 2023). "The EGFR signaling pathway was activated in more than half of NSCLC patients and was important in cancer cell proliferation and invasion." (PMID 38008767, 2023). "Targeted therapies, such as EGFR inhibitors and ALK inhibitors, selectively target cancer cells while sparing normal cells, resulting in improved efficacy and fewer side effects compared to traditional chemotherapy." (PMID 37580790, 2023). "For example, SRC can enhance the phosphorylation of epidermal growth factor receptor (EGFR) and promote cell transformation and cancer development." (PMID 37172717, 2023). "Monoclonal antibodies, such as cetuximab, have a 10-fold higher affinity for EGFR than natural ligands and can prevent EGF from binding to its receptor, making them an effective targeted therapy for these cancers." (PMID 38148845, 2023). "Safety is of great importance as efficacy in assessing the role of an innovative combination due to most patients with advanced NSCLC ultimately die of their cancer, such as SFI plus EGFR-TKIs studied in this current research." (PMID 36008690, 2023). "This has resulted in the creation of a whole range of modern drugs that significantly improve the results of cancer treatment (e.g., estrogen receptor (ER) and androgen receptor (AR) antagonists, BCR-ABL, HER2, EGFR inhibitors, etc.)." (PMID 38136555, 2023). "The expression of epidermal growth factor receptor (EGFR), a regulator of cell growth in tissues of epithelial origin, is often elevated in various cancers." (PMID 37893171, 2023). "A llama anti-CD16 nanobody was fused to three different nanobodies targeting CD19, HER2, and EGFR cancer antigens to create anti-CD16/CD19, anti-CD16/HER2, and anti-CD16/EGFR BiKEs, respectively." (PMID 36761751, 2023). "In cancer cells, ROR1 cooperates in pro-survival pathways such as PI3K/AKT, EGFR, and MET signaling to enhance tumor cell growth and survival, EMT (epithelial–mesenchymal transition), and metastasis." (PMID 37400436, 2023). "For example, the amplification of the HER2 gene can lead to the rapid growth and spread of cancer cells, and the expression of BRCA1, BRCA2, EGFR, and PIK3CA can also increase the proliferation and migration risk of cancer cells." (PMID 37960513, 2023). "To identify genes integral for high EGFR TKI sensitivity, we used CCLE (Cancer Cell Line Encyclopedia) and PRISM (profiling relative inhibition simultaneously in mixtures) to cross-screen for common TKI sensitive genes." (PMID 37542131, 2023). "Currently, the widely investigated formulations that often are composed of ligand-targeted components facilitate the binding to EGFR, PSMA, transferrin, folate receptors, etc., but most human cancers still cannot be imaged." (PMID 37151801, 2023).
cancer (continued). "WNT/β-catenin signaling controls cellular signaling cascades, including epidermal growth factor receptor (EGFR), Hippo/YAP, nuclear factor kappa-B (NF-kB), Notch, Sonic Hedgehog, and the PI3K/Akt pathway, which are involved in cancer development." (PMID 37240338, 2023). "Specifically, the molecules involved in cancer-related pathways, including LAMB3, KEAP1, Bid, EGFR, Bcl-XL, Bcl-2, and PAX8, were all regulated by JorA." (PMID 37587470, 2023). "EREG, one of the ligands of EGFR, has a low expression in most normal tissues; however, in cancer, EREG up-regulates and activates EGFR." (PMID 37670265, 2023). "Recent progress in cancer genomics revealed that OSCC exclusively or over-expressed various surface receptors, such as epidermal growth factor receptor (EGFR), facilitating the application of molecular targeted therapy with improved selective toxicity." (PMID 38258044, 2023). "Numerous small molecule TKIs and mAbs targeting EGFR and HER2 were developed and approved for cancer treatment." (PMID 37631380, 2023). "The transactivation process occurs rapidly after adding NTS to cancer cells, and when tyrosine1068 of the EGFR is phosphorylated, the MEK/ERK pathway is activated, leading to increased cancer cellular proliferation." (PMID 37508387, 2023). "Our data calls for high-throughput screening of various cancer cell lines in combination treatment with AICAR, JAK, or EGFR inhibitors." (PMID 36810913, 2023). "Many pharmaceutical companies developed small-molecule inhibitors and monoclonal antibodies against EGFR and HER2 because of their pro-oncogenic function in different types of cancer." (PMID 37947595, 2023). "According to the findings of this study, miR-7 had different expression levels before and after treatment, and these miRNAs targeted the key genes such as EGFR, AKT, and Rel-A, which all were involved in cancer radiation." (PMID 37507347, 2023). "We also analyzed the evolutionary dynamics of six cancer pathways of two major axes: Notch/WNT/Hedgehog and AKT/mTOR/EGFR." (PMID 37174700, 2023). "In other types of cancer, HA-CD44 binding also plays a role in triggering signals from later receptors in the tyrosine kinase family (such as EGFR), leading to PI3K/Akt or MAPK pathway activation." (PMID 37445716, 2023). "Monoclonal antibodies (MoAbs) and antibody–drug conjugates have been widely used in targeting EGFR and HER2 in different cancers." (PMID 37947595, 2023). "Another factor that is specific to many types of cancer, including GBM and NSCLC, is the epidermal growth factor receptor (EGFR)." (PMID 37687164, 2023). "In particular, the administration of metformin, which has been proposed as a repurposed drug for cancer treatment, alleviates IL-1RA-promoted OSCC malignancy through EGFR/JNK signaling and SOX2 expression." (PMID 37461111, 2023). "Monensin has been reported to suppress many cancer-related pathways such as those involving β-catenin/Wnt, E2F/DP1, STAT1/2, NFkB, AP-1 and Elk-1/SRF, and to downregulate EGFR expression, especially in pancreatic cancer lines." (PMID 37046746, 2023). "Fucosylation enhances EGFR and TGFR signaling by regulating ligand binding affinity and cell membrane trafficking, inducing cancer cell proliferation and metastasis." (PMID 37612293, 2023). "EGFR-dependent cancers have a unique dependence on Wnt signaling following EGFR inhibition, suggesting that SRPK1 is a key node linking EGFR with the Wnt pathway." (PMID 36869126, 2023). "The major EGFR downstream target, the Ras/RAF/MEK/ERK (MAPK) signaling pathway, plays a crucial role in the survival, growth and proliferation of cancer cells, and its hyperactivation is responsible for over 40% of human cancer cases." (PMID 37626832, 2023). "In this work, we also showed that angiogenin and its two recently identified receptors, EGFR and PLXNB2,45,58 were upregulated at the protein level by ccRCC cancer cells as compared to their cell type of origin ex vivo." (PMID 38025776, 2023).
cancer (continued). "To evaluate the impact of cSNX1.3 on an immune intact mouse model of cancer, we utilized WAP-TGFα mice, a transgenic line whose mammary gland tumors are EGFR dependent." (PMID 36253541, 2023). "In ALK‐rearranged primary cultures, the combined inhibition of ALK and PI3Kβ prevented the EGFR‐mediated ALK‐inhibitor resistance, and selectively targeted the cancer cells." (PMID 36423211, 2023). "The investigation of novel EGFR and BRAFV600E dual inhibitors is intended to serve as targeted cancer treatment." (PMID 37242499, 2023). "Although EGFR and HER2 are widely known targets for therapy in cancer, HER3 has long been underestimated for cancer therapy." (PMID 37947595, 2023). "Another example is Cbl Proto-Oncogene C (CBLC), which has evidence of interacting with the major oncogenes, EGFR and ERBB241, and was highly expressed in 12 cancer types at transcriptomic and proteomic levels, and lowly expressed in most normal tissues." (PMID 37845222, 2023). "The Epidermal Growth Factor Receptor (EGFR) pathway remains one of the most successfully and effectively targeted signaling pathways in cancer treatment." (PMID 37687086, 2023). "Among these potential druggable alterations, EGFR, KRAS, and PIK3CA gene alterations were the most common, while CDK pathway (CDK4/6, CDKN2A/2B), FGFR1/2/3, BRAF, RET was uncommon across pan-cancer." (PMID 36910668, 2023). "Gene expression analyses provided insights into the molecular mechanisms underlying AV25R’s effects, revealing a multitude of differentially expressed genes and significant regulation of cancer-related pathways such as VEGFA-VEGFR2 and EGF/EGFR." (PMID 38138609, 2023). "We found that cancer cell lines with high SYK expression showed sensitivity to inhibition of both c-Met and EGFR." (PMID 37183231, 2023). "Many malignant tumors, including NSCLC, have been found to carry mutants and amplifications in the EGFR gene." (PMID 38162667, 2023). "Understanding the roles of EGFR and HER2 in cancer proliferation is crucial for developing effective therapies that can target these proteins and overcome drug resistance." (PMID 37242487, 2023). "For example, the upregulation of oncogenes in cancer cells can increase their exosome oncoprotein levels, such as HRS and EGFR type III." (PMID 37287924, 2023). "The epidermal growth factor receptor (EGFR) is a key regulator in cell proliferation, differentiation, division, survival, and cancer development." (PMID 37627119, 2023). "More specifically, the activation of EGFR signaling mediated by Src promotes RAS activation, one of the essential signals for cancer cell growth, differentiation, and survival, and consequently induces the upregulation of NF-κB." (PMID 37686097, 2023). "Most genes were significantly correlated with gastric inflammation-cancer transformation, such as AKT1, EGFR, and MYC." (PMID 37964307, 2023). "Tyrosine kinase inhibitors such as osimertinib, erlotinib, and gefitinib target the ERRB/EGFR, and antibodies such as trastuzumab, which target the ecto-domain of ERBB2, have been developed as therapeutics such as ERBB2-overexpressing cancers." (PMID 37359373, 2023). "HER-1 (or EGFR) is also a member of the transmembrane receptor family and is a vital mediator of cancer cell transformation, proliferation, survival, adhesion, migration, maintenance, and differentiation." (PMID 36979567, 2023). "It was demonstrated that in cancer cells A549 and MGC823, cyasterone blocked EGFR phosphorylation in a concentration-dependent manner, further inhibiting its downstream AKT phosphorylation." (PMID 37853474, 2023). "Since HDACs have significant connections with pro-tumoural cell signalling pathways, such as EGFR and PI3K, HDAC inhibitors have been given clinical attention for their ability to reset the epigenetic profiles that regulate cancer hallmarks." (PMID 37857607, 2023).
cancer (continued). "In this study, we investigate the potential of repurposing furmonertinib, an epidermal growth factor receptor (EGFR) tyrosine kinase inhibitor (TKI), as a candidate for reversing MDR mediated by ABCB1 and ABCG2 in multidrug-resistant cancer cells." (PMID 37762275, 2023). "Among these four members of RTKs, EGFR and HER2 are the most studied targeted molecules in cancer therapy." (PMID 37947595, 2023). "In response to EGF ligand stimulation, DSG2 is known to be involved in the activation of EGFR, c-Src and Signal transducer and activator of transcription (STAT3), which supports cancer cell growth and migration." (PMID 38188287, 2023). "Epidermal growth factor receptor (EGFR), transforming growth factor-beta (TGF-β), and tumor necrosis factor-alpha (TNF-α) ligands were reported for stimulating cancer cell progression and survival." (PMID 37893013, 2023). "MT4-MMP is thought to stimulate cell proliferation by interacting with EGFR and enhancing its activation by its ligands, the epidermal growth factor (EGF), and tumor growth factor (TGF) in cancer cells." (PMID 37373092, 2023). "CP-358,774 is a novel potential and selective inhibitor of EGFR and inhibits EGF-mediated mitogenesis in cancer cells." (PMID 36646686, 2023). "In this sense, EGFR signaling as a driver or modulator of liver inflammation in CLD and cancer should be taken into consideration when thinking about EGFR inhibition to combat HCC." (PMID 38138981, 2023). "For cancer cells to multiply, the extracellular signal-regulated protein kinases ERK1/2 and the epidermal growth factor receptor (EGFR) must both be activated." (PMID 38129839, 2023). "EGFR, HER2, and HER3 stimulate cancer proliferation, principally by activating the phosphatidylinositol-3-kinase and extracellular signal-regulated kinase (ERK) pathways, resulting in increased cancer cell survival and proliferation." (PMID 37508387, 2023). "Alteration of common oncogenic proteins, such as epidermal growth factor receptor (EGFR), KRAS, BRAF, and c-Myc, drives tumorigenesis across 38 cancer types." (PMID 36694209, 2023). "Although neuropilins primarily function as vascular endothelial growth factor (VEGF) coreceptors in cancer, their interactions with CDK4, EGFR, RAS, BRAF, PI3K, and PTEN are not fully understood." (PMID 37885828, 2023). "Overall, our results suggest that SOX (4a) targets CD-44, EGFR, AKR1D1, and HER-2 and induces ROS generation in cancer cells." (PMID 37108498, 2023). "Pharmacologic inhibition of the EGFR, mTORC1 and ATR pathways represent therapeutic options in several cancer types." (PMID 37202753, 2023). "Overall, we demonstrate that EGFR, ERBB2 and ERBB4 fusions are present across numerous cancer types and importantly are excellent candidates for targeted therapy development." (PMID 37168365, 2023). "EpCAM was closely associated with various vital signaling pathways as Wnt, transforming growth factor beta (TGF-β)/SMAD, EpEX/EGFR, and PI3K/Akt/mammalian target of rapamycin (mTOR) which regulate cancer cell adhesion, proliferation, invasion, and survival." (PMID 37457288, 2023). "EGFR TKIs can lower PD-L1 expression in EGFR-mutant NSCLC cells, making PD-1/PD-L1 inhibitors ineffective for most patients with this type of cancer." (PMID 36835536, 2023). "Moreover, the activation of signaling pathways involved in sustaining cancer proliferation, including EGFR, HER2, B-RAF, ERK, mTOR, AKT, and SRC, have been identified in association with ADPKD, accumulating evidence that polycystins may be involved in cancer development and progression." (PMID 37510333, 2023). "The EGFR-AKT-PI3K-mTOR axis plays a central role in cellular growth and metabolism and is frequently altered in cancer." (PMID 36977662, 2023).
cancer (continued). "HER4 has both growth stimulatory and growth inhibitory properties, whereas the EGFR, HER3, and HER2 stimulate cancer growth." (PMID 37508387, 2023). "One study used anti-EGFR nanobodies, of approximately 31 kDa, to guide red blood cells vesicles (RBCEVs), and their results revealed high affinity of the construct to EGFR-positive cell lines such as H358 and HCC827 (cancer lung cell lines)." (PMID 37375810, 2023). "This study focuses on virtually screening phytochemicals from Conium maculatum as potential inhibitors of the epidermal growth factor receptor (EGFR), a crucial target in cancer therapy." (PMID 38034159, 2023). "Based on the different properties of these agents, it is possible that afatinib, due to its potent and prolonged inhibition of EGFR in addition to its inhibition of HER2, provided a better effect than lapatinib on cancer with HER2 E401G." (PMID 36690964, 2023). "Intriguingly, T-1-MTA inhibited the EGFR protein with an IC50 value of 22.89 nM and demonstrated cytotoxic activities against the two cancer cell lines, A549, and HCT-116, with IC50 values of 22.49, and 24.97 μM, respectively." (PMID 36893122, 2023). "Cyclin D1, epidermal growth factor (EGFR) and vascular endothelial growth factor (VEGR) are common carcinogenic proteins that have potential therapeutic targets in various cancers." (PMID 38414954, 2023). "Present Studies revealed that apoptotic ability of TGF-β1is accelerated when cells treated with the extract of Artemisia absinthium by inhibiting the EGFR and PK13/AKT pathway that leads to cancer activity in normal cells." (PMID 37053209, 2023). "Epidermal growth factor receptor (EGFR) and human epidermal growth factor receptor 2 (HER2) are two proteins that play a significant role in cancer proliferation." (PMID 37242487, 2023). "Curcumin, a naturally occurring polyphenol derived from turmeric, demonstrates anti-cancer properties through modulating various molecular targets such as STAT3, EGFR, PI3KAkt/mTOR, E-cadherin, MMPs, and COX-2." (PMID 36831374, 2023). "EGFR (epidermal growth factor receptor) and BRAF (B-Raf proto-oncogene, serine/threonine kinase) are both well-studied kinases that play crucial roles in cancer progression." (PMID 37240450, 2023). "HER3 mediates resistance to EGFR, HER2, PI3K/AKT/mTOR directed therapies and endocrine therapy and its allosteric function is critical for HER2-amplified cancer growth." (PMID 36966267, 2023). "Unfortunately, most patients who initially respond to EGFR-TKI ultimately develop resistance to therapy, resulting in cancer progression and relapse." (PMID 38033496, 2023). "These synthesized analogs showed promising anti-proliferative and dual inhibitory activity, targeting the EGFR and MAPK pathways in a panel of cancer cell lines." (PMID 37687086, 2023). "Here the authors investigate E3 ligases—key to PROTAC function—and identify candidate targets for cancer drivers such as KRAS and EGFR." (PMID 37845222, 2023). "Another major factor in various human cancers is the epidermal growth factor (EGF) and its correlating receptor, the epidermal growth factor receptor (EGFR)." (PMID 37623256, 2023). "successfully infused CAR-T cells targeting epidermal growth factor receptor (EGFR) and CD133 into a patient with metastatic CCA and achieved small increases in overall survival and cancer cell death, especially when combined with other therapies." (PMID 37138880, 2023). "EGFR-mediated STAT3 signaling activation promotes the proliferation and glycolysis in various cancers." (PMID 37944197, 2023). "Many other proof-of-concept studies have also been carried out for developing Nb expressing CAR T-cells that target other cancer biomarkers such as CD20, EGFR, and HER2." (PMID 36983063, 2023). "The apoptotic effect of EGFR can also lead to biased signaling downstream by STAT1 and STAT3 activation in cancer cell lines." (PMID 37259433, 2023).